ARID1A (AT-rich interaction domain 1A)
Diseases named in the same sentence as ARID1A in open-access papers (continued):
Sharing a sentence is not in itself a finding about the gene and the disease.
cancer (continued). "Hence, the observed clinical response seen here upon mono- and combination therapy with α-PD-L1 adds another piece of evidence for the causative relevance of ARID1A mutations in dMMR-driven cancers." (PMID 34206051, 2021). "Thus, ARID1A-deficient cancer cells have low basal levels of glutathione, which make these cancer cells specifically vulnerable to inhibition of the glutathione-SH (GSH) metabolic pathway." (PMID 33401771, 2021). "Latest studies discovered several novel targets for the treatment of ARID1A-mutated cancers." (PMID 34715776, 2021). "In ARID1A-deficient cancer cells, GSH level decreases due to the impairment of solute carrier family 7 member 11 (SLC7A11), the gene encoding cystine transporter that is required for incorporation of cystine and supplies cells with cysteine, a key source of GSH." (PMID 34671561, 2021). "Mutation frequency of ARID1A gene in different human cancers." (PMID 34671561, 2021). "Interestingly, co-occurring landscapes of genetic mutations reported in ARID1A-mutated cancers were completely different in early-stage versus advanced-stage cancer." (PMID 34257552, 2021). "Clinical trials involving patients with ARID1A-mutated cancer." (PMID 34804958, 2021). "In addition, the malignant risk is higher and the cancer progresses faster in the Brg1 (3/7 at 9 w) knockout model than in the Arid1a knockout model (3/15 at 48 w), suggesting a more important role of Brg1 than Arid1a in invasive IPMN." (PMID 34771461, 2021). "Indeed, ARID1A is the most commonly mutated SWI/SNF subunit in cancer, altering transcriptional regulation that cannot be covered by the ARID1B paralog." (PMID 34070411, 2021). "Understanding how loss of ARID1A creates stresses on dividing cancer cells provides new opportunities to develop or apply therapies that could exploit this stress." (PMID 33826602, 2021). "ARID1A is one of the most frequently mutated epigenetic regulators in a wide spectrum of cancers." (PMID 33983114, 2021). "In this review, we concluded a series of the published studies that focused on ARID1A in cancers and proposed the underlying mechanisms related to the resistance to EGFR-TKIs induced by ARID1A alterations or expression loss and the potential therapeutic strategies to overcome the resistance." (PMID 34715776, 2021). "Therefore, it is crucial to study the ubiquitous mechanisms for ARID1A-deficiency-facilitated tumorigenesis in various types of cancers." (PMID 33983114, 2021). "It is thought that ARID1A-mutated cancers may cooperate with immune checkpoint blockade therapy, thus providing novel therapeutic strategies for cancer management." (PMID 33227989, 2020). "According to the latest studies, ARID1A deficiency may be a novel biomarker for cancer immunotherapy, and patients with ARID1A deficiency could benefit from ICIs treatment." (PMID 32791957, 2020). "Loss of ARID1A expression is frequent in many types of cancers." (PMID 32334542, 2020). "Somatic mutations in the ARID1A subunit of the SWI/SNF complex frequently occur in human cancers." (PMID 32483112, 2020). "The association between ARID1A mutations and cancer subtypes with profound lymphocytic infiltration raises the possibility that ARID1A mutations may boost the ability of cancer cells to escape from immune surveillance." (PMID 32162380, 2020). "Since mutations of Kit and Arid1a coexisted in various cancers, it is critical to notice if there could be any signs of other tumorigenesis in our patient during follow-up therapy." (PMID 33327223, 2020).
cancer (continued). "Among different chromatin remodelers, SWI/SNF complexes, with an estimated mutation frequency of 20%, are the most commonly dysregulated epigenetic complexes in cancer, and AT-rich interactive domain-containing protein 1A (ARID1A) is the most frequently mutated gene subunit." (PMID 31906887, 2020). "Furthermore, we explored the correlation between ARID1A mutations and immune checkpoint blockade therapy response using three cancer immunotherapy (anti-PD-1/PD-L1/CTLA-4) response-associated cohorts (Allen cohort, Hugo cohort, and Samstein cohort)." (PMID 31277418, 2019). "Conversely, ARID1A loss may increase the risk for steatohepatitis and cancer progression by altering immunity in vivo or tumorigenesis by activating angiopoietin-2 (ANGPT2) transcription in vitro and causing angiogenesis in vivo." (PMID 31238554, 2019). "The appearance of new mutations in PDX1 might be the consequence of some degree of clonal selection during in vivo growth, since mutations of ARID1A are associated with increased cellular proliferation and have been reported in a variety of human cancers." (PMID 31216647, 2019). "The BAF-specific ARID1A gene is the most commonly mutated SWI/SNF component in cancer." (PMID 31123059, 2019). "ARID1A ranks top among the mutated chromatin regulator across all human cancers." (PMID 31731647, 2019). "Whether this provides a real opportunity for ARID1A-deficient MMR-D-related cancer will need to be tested prospectively." (PMID 31581674, 2019). "Therefore, targeting EZH2 methyltransferase activity provides a personalized strategy for ARID1A-mutated cancers." (PMID 31238554, 2019). "In this way, HDAC inhibitors could be another anti-cancer agent for treating ARID1A-mutated cancers." (PMID 31238554, 2019). "Besides a number of immune-related pathways, many cancer-associated pathways were upregulated in ARID1A-mutated GI cancers versus ARID1A-wildtype GI cancers, identified by GSEA." (PMID 31277418, 2019). "Furthermore, we found that ARID1A-mutated cancers likely exhibited a better survival prognosis than ARID1A-wildtype cancers in the immunotherapy setting." (PMID 31277418, 2019). "ARID1A deficiency has been shown to sensitize cancer cells to PARP inhibitor, BMN673." (PMID 31731647, 2019). "The reason behind this observation could be that the elevated immune activity and PD-L1 expression promote the immunotherapy response in ARID1A-mutated cancers." (PMID 31277418, 2019). "Moreover, we compared the overall survival (OS) between ARID1A-mutated and ARID1A-wildtype cancers in the three cohorts." (PMID 31277418, 2019). "Together, we conclude that ARID1A inactivation causes selection against the survival of cells with severe defects in telomere cohesion, which correlates with a preservation of genomic stability in ARID1A-mutated cancers." (PMID 31492885, 2019). "Inactivating mutations in ARID1A have been detected in multiple forms of human cancers." (PMID 31640753, 2019). "Thus, cancer cells deficient in ARID1A are sensitive to ROS-mediated death caused by agents that antagonize the (already diminished) levels of GSH." (PMID 31434226, 2019). "Thus, this represents a novel strategy to overcome and/or prevent the development of de novo resistance to EZH2 inhibitors in ARID1A-mutated cancers." (PMID 30297712, 2018). "In addition, ARID1A and ARID1B alleles are frequently co-mutated in cancer, but ARID1A-deficient cancer retains at least one functional ARID1B allele." (PMID 29890703, 2018).
cancer (continued). "Cancer genome sequencing has uncovered a widespread tumor suppressor role of the BAF complex, which guards against numerous cancers including colorectal cancer, with >20% of all cancers exhibiting at least one inactivating mutation in one of its subunits, most notably in ARID1A." (PMID 28296634, 2017). "Even though a very low percentage of ccRCC tumors harbor mutations in ARID1A, the high rate of ARID1A expression loss clearly indicates that it plays a critical role in cancer biology in ccRCC, and a clever way to take advantage of its loss to treat ccRCC is worth serious efforts to pursue." (PMID 28445125, 2017). "ARID1A exhibits up to a 50% mutation frequency in diverse cancers." (PMID 27980214, 2017). "Last, a growing body of evidence suggests that activation of some genes or pathways may act in concert with ARID1A loss in accelerating cancer development." (PMID 27354232, 2016). "Other therapies for ARID1A-mutated cancers include inhibition of EZH2, PI3K, or PARP." (PMID 27737960, 2016). "These trials could be conducted in cancer types where there is a high frequency of ARID1A mutations, such as OCCC, where standard of care therapeutic responses are limited and where few targeted approaches exist." (PMID 27958275, 2016). "ARID1A mutation in cancer tended to occur in a synergistic fashion with PIK3CA." (PMID 27323812, 2016). "ARID1A deficiency is associated with cancer cell proliferation and metastasis." (PMID 27323812, 2016). "The highly recurrent nature of ARID1A mutations in human cancer and the availability of clinical ATRi suggests that once Phase I clinical trials are complete, biomarker driven proof-of-concept trials could be instigated to assess this hypothesis." (PMID 27958275, 2016). "Evidences of discordance between expression and heterozygous mutations or loss of heterozygosity in cancer samples imply that reduced levels of ARID1A may be the contributing factor in promoting cancer." (PMID 26524630, 2015). "Indeed, many studies have analyzed ARID1A expression in a variety of human cancers and demonstrated loss of ARID1A expression." (PMID 26378916, 2015). "However, the detail underlying mechanism involved in genomic instability and cancer-promoting microenvironment in the Arid1a deficiency-driven HCC model should be further investigated." (PMID 26569409, 2015). "Loss of the tumor suppressor gene AT-rich interactive domain-containing protein 1A (ARID1A) has been demonstrated in several cancers, but its prognostic role is unknown." (PMID 26384299, 2015). "Despite these very heterogeneous genetic and epigenetic interactions of ARID1A with other important molecular mechanisms, our statistically significant results of the prognostic value of ARID1A mutation on cancer recurrence and death due to cancer have relevant research implications." (PMID 26384299, 2015). "This indicates that ARID1A-mutated cell clones require a second-hit mutation in order to transform into cancer, which may explain why loss of ARID1A expression was observable in a subset of non-atypical benign endometriosis in one of our previous studies." (PMID 24979463, 2014). "ARID1A mutations often occur to initiate oncogenesis in cancers with an epigenetic disposition." (PMID 25594067, 2014). "Mutations in the ARID1A gene occur in a wide variety of different cancers." (PMID 24036443, 2013). "Moreover, ARID1A exhibits the highest frequency of mutations among the subunits of human SWI/SNF complexes in cancers, and this mutation has been strongly associated with the occurrence and development of ovarian clear-cell carcinoma, colon cancer, and other types of tumors." (PMID 38761067, 2025).
cancer (continued). "Thus, we argue that the time during cancer development or progression may be crucial for the effects of the depletion of ARID1A and that early mutation, as is observed frequently, has the greatest impact on the cell." (PMID 40170512, 2025). "However, the role of Arid1a mutations in human cancers is still a topic of debate." (PMID 39123453, 2024). "Therefore, we conjecture that ICB therapy combined with ART inhibitor may be an effective treatment strategy for ARID1A-deficient cancer." (PMID 38347608, 2024). "Consequently, EZH2 inhibitor-resistant ARID1A-mutated cells become highly sensitive to BCL2 inhibitors like ABT263 suggesting that BCL2 inhibition alone or in combination with EZH2 inhibition represents an improved therapeutic strategy for ARID1A-mutated cancers." (PMID 39471843, 2024). "Previous studies have suggested that ARID1A deficiency may contribute to cancer development." (PMID 38835016, 2024). "Based on these findings, we hypothesized that cancer-promoting mutations (i.e., ARID1A) increase PRC2 complex activity (including expression of the EZH2 component) and induce an HCV/alcohol-mediated stem cell program (slow growing cells), leading to TIC-initiated HCC development." (PMID 37744383, 2023). "In a previous study, next-generation sequencing (NGS) was used for mapping CCA, 182 cancer-associated genes and 37 introns were identified from 14 cancer-rearranged genes, which demonstrated that biliary tract tumors share the same chromatin remodeling (ARID1A) and genomic aberrations (CDKN2B)." (PMID 36936931, 2023). "Considering the growing list of synthetic lethal gene pairs with ARID1A deficiency, it may be interesting to investigate the efficacy of combinational therapy of PLK1 inhibitor and agents targeting synthetic lethal phenotypes in ARID1A-mutated cancers, such as PARP inhibitors and ATR inhibitors." (PMID 36980292, 2023). "Studies, both preclinical and clinical, have demonstrated that the role of genetics and epigenetics in malignant tumors will be explored further, and mutation of the chromatin remodeling complex subunit, ARID1A, may become a promising tool for individualized treatment targets in patients with GC." (PMID 38008753, 2023). "Therefore, ARID1A mutant cancers are highly susceptible to the inhibition of PI3K and AKT kinases." (PMID 37093326, 2023). "In a previous study where next-generation sequencing (NGS) was used for mapping CCA, 182 cancer-associated genes and 37 introns were identified from 14 cancer-rearranged genes, which demonstrated that biliary tract tumors share the same chromatin remodeling (ARID1A) and genomic aberrations (CDKN2B)." (PMID 37954763, 2023). "Moreover, laboratory data suggest that cancer cells with ARID1A loss may be sensitive to EZH2 and BET inhibitors." (PMID 35328145, 2022). "Notably, loss of ARID1A expression is associated with high risk or poor outcome of various cancers." (PMID 35611248, 2022). "Furthermore, in the course of carcinogenesis the loss of the tumor suppressor ARID1A may predispose early cancer cells to genomic instability." (PMID 36078038, 2022). "Thus, ARID1A deficiency has the potential as a biomarker for precision medicine in various cancers." (PMID 36123603, 2022). "Interestingly, ARID1A-deficient cancers are more sensitive to PI3K/AKT inhibitors." (PMID 35070505, 2022). "Thus, the clear distinction of pharmacological interventions targeting ARID1A may starkly differ in the prevention setting, compared to the context of cancer therapy in the face of ARID1A deficiency." (PMID 36078038, 2022). "Thus, inhibition of ATR can theoretically eliminate ARID1A-deficient cancer cells." (PMID 36123603, 2022). "In conclusion, the central role of ARID1A in the maintenance of epithelial cell identity indicates a strong potential for the therapeutic targeting of epigenetic mechanisms and chromatin accessibility for the reduction of cancer risk and tumorigenic transformation." (PMID 36078038, 2022).
cancer (continued). "Additionally, it was also revealed that ARID1A alterations were associated with high TMB levels across cancer types and may cooperate with ICI treatment." (PMID 33525614, 2021). "Thus, ARID1A mutation has potential as a biomarker for precision medicine of related cancers." (PMID 34671561, 2021). "Other data suggest that immunotherapy might be a rational therapy for ARID1A-deficient carcinomas." (PMID 34200508, 2021). "Furthermore, ARID1A deficiency is correlated with a microsatellite instability genomic signature, a predominant C>T mutation pattern and an increased mutation load across multiple human cancer types." (PMID 32162380, 2020). "These latter molecules might also be highly effective toward ARID1A-deficient cancer cells." (PMID 32978257, 2020). "In addition to immunotherapy, targeted therapies against ARID1A mutations could provide significant therapeutic benefits in cancer because ARID1A is one of the most frequently mutated genes in various types of cancer." (PMID 31043675, 2019). "Thus, the consequences of ARID1A loss in cancer appear to be particularly context-dependent." (PMID 31217031, 2019). "Therefore, ARID1A deficiency has been exploited therapeutically for treating cancer." (PMID 30097580, 2018). "In addition, our data demonstrated that BCL2 inhibitors alone or in combination with EZH2 inhibitors may represent therapeutic strategies for ARID1A-mutated cancers." (PMID 30297712, 2018). "Furthermore, we speculate that loss of ARID1A could be involved in the progression of cancer or be correlated with locally invasive growth, mechanisms that could have less importance when a cancer is in a late stage." (PMID 26384299, 2015). "The expression of ARID1A may also be associated with different cancer stages." (PMID 26384299, 2015). "Thus, due to this complex interplay between partially offsetting interactions, it will be important for better understanding the prognostic role of ARID1A to identify the stages and subgroups in different types of cancers that can be affected by ARID1A mutational status." (PMID 26384299, 2015). "Future research should validate these kinase-substrate interactions and explore their transcriptional and chromatin-level impacts to develop precision therapies for ARID1A-dysregulated cancers." (PMID 41572083, 2026). "METTL8 is a methyltransferase that catalyzes RNA base modifications, including m3C and m6A, and has been shown to promote cancer cell migration through direct interaction with ARID1A, a key chromatin remodeler." (PMID 41516402, 2026). "ARID1A, encoding the most frequently mutated subunit of the SWI/SNF complex across cancer types, is frequently mutated in normal and non‐tumorous tissues, including morphologically normal liver and chronic liver diseases." (PMID 41133886, 2026). "ARID1A‐ARID1B synthetic lethality provides a therapeutic window in ARID1A‐mutant cancers, analogous to EZH2‐PRC2 disruption via peptide‐mediated interference." (PMID 41578412, 2026). "The SWI/SNF chromatin complex consists of multiple subunits, with ARID1A being a key component that is frequently inactivated in cancer." (PMID 41537447, 2026). "The ARID1A gene encodes a component of the SWI-SNF chromatin remodelling complex and is subject to loss-of-function mutations in a range of cancer types, including ovarian, endometrial, colorectal, lung, and breast cancers." (PMID 40723241, 2025). "For instance, combining ATR inhibitors with immune checkpoint blockade is being investigated in preclinical models, showing promising synergistic effects in ARID1A-mutant cancers." (PMID 39858102, 2025). "The ARID1A protein performs its primary function across different cancers by positioning cBAF at tissue-specific regulatory elements." (PMID 41514650, 2025).